BBOX1-AS1 (BBOX1 antisense RNA 1)
Gene: Long non-coding RNA gene on chromosome 11 (27,046,855 to 27,234,196, reverse strand). Ensembl gene ENSG00000254560.
Diseases named in the same sentence as BBOX1-AS1 in open-access papers:
BBOX1-AS1 is named in the same sentence as 4 diseases in open-access papers, as found by Europe PMC text mining. Sharing a sentence is not in itself a finding about the gene and the disease. The quoted sentences say what the papers report.
ovarian carcinoma (2 papers, 2022 to 2023). A malignant neoplasm originating from the surface ovarian epithelium. "LncRNA BBOX1 antisense RNA 1 (BBOX1-AS1) was reported to participate in ovarian cancer, while its role in other ovarian disorders is unclear." (PMID 35188872, 2022). "Long non-coding RNA (lncRNA) BBOX1 antisense RNA 1 (BBOX1-AS1) was reported to participate in ovarian cancer, while its role in other ovarian disorders is unclear." (PMID 35188872, 2022). "We predicted that miR-19b could bind to BBOX1 antisense RNA 1 (BBOX1-AS1), a lncRNA with a critical role in ovarian cancer." (PMID 37735639, 2023). "We speculated that miR-19b could potentially form a binding relationship with BBOX1 antisense RNA 1 (BBOX1-AS1), a long non-coding RNA recognized for its critical role in ovarian cancer." (PMID 37735639, 2023).
clear cell renal cell carcinoma (1 paper, 2023). "Moreover, studies have demonstrated that a decrease in the expression of BBOX1 antisense RNA 1 (BBOX1-AS1) corresponds to diminished cellular viability and proliferation, and low BBOX1 expression serves as a prognostic biomarker for clear cell renal cell carcinoma (RCC)." (PMID 37808522, 2023).
BBOX1-AS1 also shares sentences with these, for which no sentence is quoted: ovarian disorder (1 paper); tumor (1).